MUC1 (mucin 1, cell surface associated)
Diseases named in the same sentence as MUC1 in open-access papers (continued):
Sharing a sentence is not in itself a finding about the gene and the disease.
tumor (continued). "Recently published experiments on the chemokine axis and related tumor aggressiveness confirm differential regulations for CXCR4 and CXCL12 in NCI-H295R and MUC-1, which also suggest varying potential in terms of metastasization." (PMID 35764904, 2022). "Such as HER2, MUC1, EGFR as tumor targets of pan-cancer, are also highly expressed in BC tissues and can be used as a therapeutic target of BC." (PMID 35860578, 2022). "At present, most of the research on MUC1 and BCG is targeting MUC1 and building tumor vaccines based on BCG to better play the role of BCG." (PMID 35879749, 2022). "Preliminary analysis showed that of the patients who received ADT followed by docetaxel and then PROSTVAC, 31%, 50%, and 50% had CD4/CD8 responses to tumor antigens PSA, MUC-1, and brachyury, respectively." (PMID 36497086, 2022). "Here, at first, the role of mucins in tumorigenesis is discussed; then, it is focused on the important crosstalk of MUC1/HER2, promoting trastuzumab resistance in tumor cells." (PMID 35248049, 2022). "The use of MUC1 as an active targeting ligand to deliver DOX with SPIONs and iron carrier couples provides a suitable DDS for tumor diagnosis and targeted anti-cancer drug delivery." (PMID 35953863, 2022). "We compared the regular anti-MUC1 antibody CIM301-1 to the defucosylated CIM301-8 antibody in degranulation and cytotoxicity assays against two MUC1-Tn+ tumor cell lines." (PMID 34070311, 2021). "In summary, in the prognostic signature, some genes (MUC1, RGS4) have been reported to promote tumor cell growth." (PMID 33889544, 2021). "Tumor immunohistochemical analyses were presented as follows: Inhibin-α (-), ER (-), Vimentin (mesenchyme +), CK7 (+), CK19 (+), CK20 (−), CEA (−), MUC-1 (+), MUC-5AC (+), MUC-6 (+), MUC-2 (−), S-100p (focal+), and Ki-67 (12% +)." (PMID 33592896, 2021). "In contrast, three membrane‐bound MUCINs (MUC1, MUC13, and MUC15), one atypical MUCIN (EMCN), and one secretion MUCIN (MUC6) were significantly downregulated in the tumor samples (p < 0.05)." (PMID 34327857, 2021). "Using two different tumor models, we were able to show that, in MUC1KO host, the MDSC numbers and function is increased as compared to its WT counterpart with intact MUC1." (PMID 34070449, 2021). "MUC1-specific CAR-pNK therapy presented good safety profile and preliminary efficacy in preventing both tumor relapses and graft versus host disease." (PMID 33407739, 2021). "Mucin-1 (MUC1), a high molecular weight glycoprotein, has become a potential tumor biomarker used in tumor diagnosis and biological treatment due to its abnormal expression in various tumor tissues." (PMID 34976785, 2021). "In summary, our research shows that MUC1 is often up-regulated in ICC and promotes tumor progression by activating the Wnt/β-catenin signaling pathway." (PMID 34729096, 2021). "As classic tumor biomarkers, YBX1 and MUC1 are significant in the occurrence and development of various tumors." (PMID 34976785, 2021). "To explore the potential role of MUC1 in ICC, we first evaluated the mRNA expression of MUC1 in 30 pairs of ICC samples and matched non-tumor liver tissues." (PMID 34729096, 2021). "First, we incubated Jurkat tumor cells alone with increasing concentrations of humanized anti-MUC1 (CIM301-8) antibody and determined the level of saturation of the MUC1 epitopes and direct toxicity to tumor cells." (PMID 34070311, 2021). "Luminal eosinophilic secretions within CRC tumour glands stain differently to PAS, MUC1 and MUC2, suggesting differences in tumour biology." (PMID 34314467, 2021). "Directly silencing of either MUC1 or NRG1 by siRNA significantly inhibited NSCLC cell growth and tumour formation in vitro and in vivo, implying that they can be used as potential therapeutic targets for NSCLC." (PMID 33539648, 2021). "For these analyses, we excluded tumor-associated markers expressed in more than 90% (CK7, CK19, CKLMW, CKHMW, and MUC1) or less than 10% (vimentin and MUC2) of the tumor samples." (PMID 33494186, 2021).
tumor (continued). "In this study, we demonstrated that the 5E5-based, humanized anti-MUC1 antibodies CIM301-1 and CIM301-8 are potent enhancers of NK cell activation and cytotoxicity against MUC1-Tn/STn positive tumor cells in vitro." (PMID 34070311, 2021). "He then received dendritic cells (DCs) pulsed with MUC1, MAGE3, and survivin, which were expressed on his tumor cells as tumor antigens, 12 times at 2–3-week intervals from 26 December 2018 to 28 June 2019." (PMID 33827668, 2021). "Thus, we hypothesized that lack of MUC1 and its association with increased MDSCs enhances the numbers of Tregs in the tumor." (PMID 34070449, 2021). "However, only one study by Van Elssen differentially explored the expression of tumour-associated MUC1; other studies did not comment on the structural differences to MUC1 and thus may not be truly representative of tumour-associated MUC1 in MOC." (PMID 34830751, 2021). "In conclusion, this is the first study evaluating a multi-marker panel of mRNAs, including tumor cell-specific (CEA, CA125 and HE4) and epithelial-specific (EPCAM and MUC1) mRNAs in EOC patients before and after adjuvant chemotherapy." (PMID 34006887, 2021). "The interaction of MUC1 and ICAM1 promotes the migration of cancer cells and increases the invasive potential of tumor cells." (PMID 34770912, 2021). "Previous studies have found that the expression levels of MUCINs, including MUC1, MUC4, MUC12, MUC13, MCAM, and LAMA4 were correlated with poor survival of ccRCC patients, and/or promotion of tumor cell proliferation in vitro." (PMID 34327857, 2021). "Collectively, our results indicated a better clinical significance of tumor-specific markers (CEA and HE4 mRNAs) compared to epithelial-specific markers (EPCAM and MUC1 mRNAs)." (PMID 34006887, 2021). "Among these ten genes, the expression levels of SETD1B, ACSF2, MUC1, KLHL24, PML, MT1G, and GPT2 were higher in tumor tissues than those in normal tissues, while HIC1, AKR1C1, and LOC390705 were lower expressed in tumor tissues." (PMID 35071242, 2021). "In this study, we explored the expression of MUC1 in human ICC cell lines and tumor tissues by quantitative real-time PCR (qRT-PCR), Western blot analysis and RNA-Seq (RNA Sequencing) analysis." (PMID 34729096, 2021). "Herein, we described a novel immunotherapy strategy by directly targeting MUC-1 and EpCAM in tumor cells through the combination of EpCAM/CD3 BsAb and MUC-1/CD3 BsAb." (PMID 34522164, 2021). "Of note, anti-tumor IgE antibodies are limited to targetable tumor antigens such as HER2, CD20, and MUC-1 as above." (PMID 34063789, 2021). "The three cell lines showed positive staining for CA 19-9, MUC1 and MUC16, with moderate to strong (2+ to 3+) intensity in more than 80% of tumor cells, with the exception of CA 19-9, which was only expressed in 20% of PUC-GBC2 cells." (PMID 32293552, 2020). "Similar to MUC1, Siglec9 can interact with MUC16 expressed on epithelial ovarian cancer cells, protecting tumour cells from immune attacking." (PMID 32322597, 2020). "(F) Representative images of a p63-positive PDA tumor stained with DAPI (blue), MPO (orange), αSMA (white), MUC1 (green), p63 (red), and overlaid (merge)." (PMID 32329713, 2020). "The results indicated that the recombinant MUC1-MBP vaccine enhanced MUC1-specific Th1 response and CTL killing activity, and increased the proportion of tumor infiltrating lymphocytes (CD4+ T and CD8+ T cells)." (PMID 32823603, 2020). "The patients had previously treated inoperable or postoperatively relapsed NSCLC and received activated DCs pulsed with either autologous tumor lysates or peptide antigens (WT1, MUC1, CEA) matched to their HLA-A type." (PMID 33679709, 2020). "Tumor vaccine fused with soluble PD-1 with the MUC1 gene showed good immunogenicity and anti-tumor effect by enhancing the activation of lymphocytes, and accumulates CD8+ tumor-infiltrating lymphocytes, resulting in reduced in tumor growth." (PMID 33208183, 2020).
tumor (continued). "To further investigate the histopathological feature of tumor organoids and how this relates to parental tissues, we performed immunohistochemistry for pancreatic markers KRT7, MUC1 and MUC5AC, and the intestinal markers KRT20 and MUC2." (PMID 33327494, 2020). "The factors released by the MUC1-ST-induced macrophages and the functional data suggests a very strong relationship between these macrophages and neutrophils, however further work is required to establish whether this relationship helps or hinders tumour growth and spread." (PMID 33149188, 2020). "Increased MUC1 expression has been demonstrated to be related to increasing TNM or Dukes stage, metastasis, poor tumor differentiation, and worse long-term survival." (PMID 32168759, 2020). "Mucin glycoprotein 1 (MUC1) expression increased during progression to EAC and followed tumor invasion." (PMID 33234735, 2020). "Immunization of mice with MUC1 fusion protein containing 5 of the tandem repeats induced antibodies but with little measurable cytotoxic T cell (CTL) responses and poor tumor protection." (PMID 32351942, 2020). "The authors found MUC-1 downregulation in C1GALT1−/−/PyMT mice, suggesting a possible involvement in the delayed onset of a tumor." (PMID 32075174, 2020). "Mucin‐1 (MUC1), also known as EMA, PEM, or CA15‐3 antigen, is a transmembrane glycoprotein that is considered a prominent target for tumor immunotherapy." (PMID 33084221, 2020). "Among them, MUC1 and MUC4 have been extensively demonstrated to be oncomucins promoting tumor aggressiveness, proliferation, and metastasis, suggesting the potential use of their expression and methylation status as independent prognosis markers." (PMID 33182511, 2020). "MUC1 is reported as a key inducer of EMT and is partially responsible for the functional switch of TGF-β from a tumor suppressor to a tumor promoter during EMT in multiple cancers." (PMID 33106534, 2020). "Knockdown of IL-17RB, MUC1 and/or MUC4 also suppresses expression of stemness-related markers, such as SOX2, Nanog, Oct-4, and CD44, and inhibited tumor sphere formation." (PMID 33082357, 2020). "On immunohistochemical staining, the tumor cells of ACC showed diffuse positivity for acinar cell markers, trypsin, and BCL10 and negativity for the ductal marker MUC1." (PMID 32891173, 2020). "MUC1 has also been shown to regulate function of transforming growth factor-β (TGF-β) and switch it from a tumor suppressor to a tumor promoter in PDA cells." (PMID 33167508, 2020). "Multiple immunogens based on sialyl-Tn-modified KLH (Theratope), sialyl-Tn-modified MUC-1 peptide, and MUC-1 protein have been used to eradicate tumor progression from a MUC-1 transgenic mouse model." (PMID 32075174, 2020). "Because her tumor's immunophenotypic profile was positive not only for MUC1 and CK7 but also for CK20 and CDX‐2, her tumor was considered ambiguous with both pancreaticobiliary‐type and intestinal‐type features." (PMID 31102323, 2019). "Immunizing mice with the human tumor antigen MUC1 fused with oxidized mannan led to the induction of tumor-specific CD8+ T cells and elimination of MUC1+ tumor cells." (PMID 30909630, 2019). "In neoplasms, inordinate NF-κB promote the expression of many vital modulators of cancer progression, such as HIF-1α, AP-1, STAT3, and MUC1." (PMID 31781219, 2019). "Compared with monovalent MUC1 or CD16 aptamers, BBiApt showed more potent avidity to both MUC1-positive tumor cells and CD16-positive immunocytes." (PMID 30699986, 2019). "1, MUC-1), etc., CTSC surface markers include CD26, CD44, CD133 and CXC chemokine receptor 4 (CXCR4), etc., circulating EMT positive tumor cell surface markers are vimentin, fibronectin, calcium adhesion protein-N and calcium adhesion protein-O and so on." (PMID 31767014, 2019). "This has been shown for tumor cells overexpressing the EMT transcription factor (TF) brachyury and the consequent upregulation of the transmembrane glycoprotein mucin-1 (MUC-1)." (PMID 31096701, 2019).
tumor (continued). "In particular, our findings uncover a role for highly-glycosylated cell surface molecules (SPN and MUC1) in hindering CD3 bsAb-induced T cell-tumor cell clustering and consequent tumor cell lysis." (PMID 31882897, 2019). "PDAC exhibits several tumor-specific antigens, such as carcinoembryonic antigen (CEA), mesothelin (MSLN), and mucin 1 (MUC1), which are promising determinants for CAR T cell therapy." (PMID 31395068, 2019). "Of note, the three tumor lesions shared the same immunohistochemical staining pattern, showing negative expression of CK7 and CK20 markers and positive expression of CDX2, MUC1, MUC2, and MUC3." (PMID 31779681, 2019). "In this study, we constructed the first bivalent bispecific aptamer BBiApt, which was made of two MUC1 aptamers and two CD16 aptamers, so that the bindings to both tumor and lymphocyte were strengthened." (PMID 30699986, 2019). "Accordingly, GALNT3/T6 KO-derived tumor tissues showed reduced staining intensity for all of GALNT6, FN1, and MUC1 when compared with the Ctrl and GALNT3 KO tissues." (PMID 31071912, 2019). "Meanwhile the expression of markers of poor prognosis (Muc1, CD146, and SOX17) and good prognosis (VDR) in the tissue of patient’s tumor tissue were consistent with corresponding cell lines." (PMID 31359275, 2019). "Both HER-2 (4.5%; p < 0.005) and MUC-1 (19%; p < 0.05) tetramers detected the TCRs on CD8 + T-cells that were primed with the tumour-specific lysate and full cocktail-matured DCs." (PMID 30283982, 2019). "Depending on the size of the studied HCCs, a significant difference in positive ratio of MUC1 was observed between S3 HCC group (tumour size 5.0–8.0 cm) (~46%) and both S1 (tumour size <2.0 cm) (~7.0%) and S2 groups (2.0–5.0 cm) (~9.0%)." (PMID 30875782, 2019). "In this study, we show that overexpression of MUC1 in human SMAD4 deleted PDA cell line BxPC3, plays an important role in the switch of TGF-β from a tumor suppressor to a tumor promoter, via a SMAD4 independent mechanism." (PMID 29467938, 2018). "Further, recent evidences suggest a role for MUC1 in metabolomic reprogramming of glutamine utilization in TNBC, which influences tumor growth." (PMID 30428522, 2018). "Bispecific targeting of MUC-1 and CD16 to mediate NK cytotoxicity cells to target tumor cells in xenograft models has shown effective tumor suppression." (PMID 30249178, 2018). "Aptamers have been used to detect a variety of cancers by targeting tumor markers, such as nucleolin, tenascin, prostate-specific membrane antigen (PSMA), MUC1, annexin A2, and matrix metalloprotease-9 (MMP-9)." (PMID 29301363, 2018). "MUC1 aptamers and HER2 aptamers were also conjugated with silica nanoparticles for targeted treatment of circulating tumor cells in breast cancer." (PMID 29617327, 2018). "Overall, the proteins with lower orders of magnitude were analyzed, and tumor marker proteins, such as MUC5AC, MUC1, and CEA, were quantified with high intensity in the dataset." (PMID 29713252, 2018). "Pancreatic cancer exhibits a number of tumor-specific antigens, such as carcinoembryonic antigen, mesothelin, HER-2, and MUC1, which are promising applicants for testing CARs T-cell therapy." (PMID 29707526, 2018). "Since STn expressing cancers are associated with increased tumor initiation, progression and chemoresistance, it is reasonable to hypothesize that STn is also present on CSC populations, especially since protein CSC markers such as MUC1 and CD44v6 are known carriers of STn." (PMID 29796189, 2018). "MiR-145 can function as a suppressor of cellproliferation and tumor metastasis through targetingmultiple oncogenes such as MYC, Kras, IRS-1, SOX2,MUC1, etc., and its expression level has beenshown in several cancer cell lines." (PMID 29633600, 2018). "MUC1 specific CAR-T cells engineered with IL-4 receptor ectodomain have shown enhanced resistance to immunosuppressive cytokines and improved anti-tumor efficacy." (PMID 29568411, 2018).
tumor (continued). "Among malignant CMTs, autoantibodies to TPI, MUC1, PGAM1, CMYC and MNSOD, were present across all tumour grades." (PMID 30361548, 2018). "To investigate if this was the case, we employed two MUC1 based immunogens forms: a soluble rMUC1 glycoprotein, produced in CHO-K1 cells and MVsMUC1, tumor-derived MVs carrying the MUC1 antigen purified from a MUC1 stable transfected cell line." (PMID 30455687, 2018). "MUC1 is a tumor antigen that can modulate EGFR activity, with EGF-dependent degradation of EGFR inhibited by co-expression of MUC1." (PMID 29464085, 2018). "MUC1-CAR T cells also show enhanced proliferation, increased IFN-Υ secretion, and enhanced anti-tumor efficacy when compared to control CAR T cells in vitro." (PMID 30031396, 2018). "We further tested the cytolytic activity of the primed T cells against multiple HLA-A2+ tumor cells lines (breast MDA-MD-231 and MCF-7 and renal A-498) and an HLA-A2- cell line (SK-OV-3), all of which are MUC1+, using a standard chromium release assay." (PMID 29415891, 2018). "The CC component consisted of a single layer of tumor cells with vesicular nuclei, obvious nucleoli that expressed CK7, CK19, Muc-1, and EpCAM." (PMID 29504997, 2018). "Investigation of candidate targets has focused on cell membrane antigens such as MUC1, CD44v6, MUC4, MUC16 (CA-125), and other tumor-specific markers that are relatively specific for CSC populations." (PMID 29796189, 2018). "Other similar studies of CAR T-cells targeting MUC1, CD24, and HER2 were tested, leading to tumor regression in mice." (PMID 29707526, 2018). "In total, we quantified approximately 4200 proteins and found that mucinous (e.g. MUC1 and MUC2) and mesenchymal proteins (such as THBS2, COL11A1, and CTHRC1) were significantly upregulated in the primary tumor compared to healthy surrounding tissue." (PMID 29901861, 2018). "Among the top dysregulated genes when comparing control and tumor free tissue were those involved in apoptosis (CIDEC, MUC1, ZBTB16, PRNP, ECT2), immune response (IFI27) and differentiation (KRT36)." (PMID 28038473, 2017). "In agreement with our in vitro data, PTX treatment induced elevated expression levels of MUC1, ABCB1, and marked increase of EGFR nuclear localization in tumor tissues." (PMID 28796259, 2017). "Importantly, α-gal(+) PDAC-associated antigens, including MUC1 and other unknown TAAs in PDAC tumor lysates, were shared with those expressed by PANC-1 cells and induced antitumor Abs by α-gal(+) PDAC tumor lysate vaccination that strongly cross-reacted with human PDAC cell lines." (PMID 29077749, 2017). "WFA-sialylated MUC1 levels in serum and bile samples from patients with either BTC or IhCC were compared with regard to pathological cancer stage and tumor tissue type." (PMID 27358229, 2017). "Anti-MUC1 CAR T cells demonstrated effective cytotoxicity and tumor growth control in xenograft models of leukemia and pancreatic cancer." (PMID 29312332, 2017). "Previously, we have shown specifically increased MUC1 levels in A549/PTX cells, and an activated AKT-related tumor growth mechanism." (PMID 29299167, 2017). "This study demonstrated that “dual-targeting” CAR T cells kill HER2+ tumor cells efficiently and proliferate in a manner that requires co-expression of MUC1 and HER2 by tumor cells, coupled with diminished damage to normal tissues expressing single antigen." (PMID 28977984, 2017). "LMP1 was also shown to induce the expression of Mucin 1 (MUC1), which plays an essential role in tumor invasion and metastasis by opposing cell adhesions." (PMID 28819752, 2017). "Collectively, these results suggest that MUC1 serves as a metabolic regulator in TNBC, facilitating the metabolic reprogramming of glutamine utilization that influences TNBC tumor growth." (PMID 28464016, 2017).